KL (klotho)
Diseases named in the same sentence as KL in open-access papers (continued):
Sharing a sentence is not in itself a finding about the gene and the disease.
tumor (continued). "Consistent with these phenotypes, reduced cell proliferation (Ki67) and reduced RAS downstream signaling, additional markers for tumor growth (pERK and pS6), were observed in G6pdKO;KL lung tumors compared to G6pdWT;KL lung tumors." (PMID 38997257, 2024). "DCC-3116-treated KL mice displayed significantly decreased tumor burden compared to control KL mice." (PMID 39213022, 2024). "Similar to Lsd1 knockout, GSK2879552 treatment obviously inhibited KL tumor progression and neutrophil infiltration." (PMID 37051524, 2023). "In tumor cells, Klotho is silenced by histone deacetylation and by hypermethylation of its promoter." (PMID 37425590, 2023). "Klotho plays a role in cancer biology by serving as both a tumor suppressor and prognostic tumor biomarker, thus preventing and detecting neoplasms." (PMID 37425590, 2023). "Klotho proteins, αKlotho, βKlotho, and γKlotho, exert tumor-suppressive activities via the fibroblast growth factor receptors and multiple cell-signaling pathways." (PMID 37958253, 2023). "As Klotho is recognized as a tumor suppressor gene, its inactivation by DNMT is a critical pathological mechanism that results in an increased likelihood of neoplasms development." (PMID 37372437, 2023). "Klotho has a pivotal function in the suppression of tumors, and it also acts as a predictive tumor biomarker with an aim to help in the preliminary detection of cancers." (PMID 37425590, 2023). "After collecting and processing the data in TCGA-KIRC database, we found KL gene in tumor tissues was downregulated." (PMID 37726833, 2023). "Treatment with soluble Klotho has been shown to reduce tumor volume in preclinical cancer models in organs such as the stomach, pancreas, colon, and breast." (PMID 37425590, 2023). "Previous studies have demonstrated that KL can suppress tumor growth, inhibit metastases, reduce resistance, and improve survival." (PMID 36091132, 2022). "The results clearly demonstrate that restoration of TUSC2 expression profoundly enhances KL tumor response to conventional chemo–immunotherapy." (PMID 35210547, 2022). "The forced expression of klotho in laboratory samples of cancer cells reduced cancer cell proliferation, while klotho silencing increased cancer cell proliferation, suggesting that klotho acts as a tumor suppressor in vitro." (PMID 36557322, 2022). "The insulin/IGF-1 pathway also plays a role in cancer progression, and its inhibition by Klotho is tumor suppressive." (PMID 35903083, 2022). "GEMMs with KL;ASC tumors had significantly higher levels of CD11b positive cells in all three compartments than GEMMs with KL;AC tumors, which had similar systemic neutrophil populations to non-tumor bearing control mice." (PMID 36355420, 2022). "Klotho’s function as a tumor suppressor has also been demonstrated in various malignancies, including colorectal, pancreatic, gastric, renal, breast, and ovarian cancers." (PMID 36220392, 2022). "In both cancer and aging, the reduction in phosphate toxicity potentially mediates klotho as both a tumor-suppressing agent and as an age-suppressing agent." (PMID 36557322, 2022). "The KL cluster, for instance had a pauci-immune tumour microenvironment and these tumours tended to have low PD-L1 expression." (PMID 36284306, 2022). "Even ample studies demonstrated the important tumor suppressor roles of KL, there is currently only limited information regarding the potential molecular mechanisms by which KL is regulated." (PMID 35468874, 2022). "Lkb1 ectopic expression in KL, KC, or KP tumors significantly reduced growth and induced apoptosis, further demonstrating the functional classification of Lkb1 as a tumor suppressor gene." (PMID 35573694, 2022).
tumor (continued). "Mice in the vehicle control group developed large ASC tumors with 75.5% lung area defined as tumor, while AF-treated mice exhibited significantly lower tumor burden (15.7%), consistent with previously observed therapeutic response in KL;ASC GEMMs." (PMID 36355420, 2022). "In this study, we aimed to decipher the role of klotho as a tumor suppressor in PDAC by utilizing three in vivo models." (PMID 34944918, 2021). "KL tumors become reliant on these metabolic and epigenetic features, and either silencing of PSAT or DNMT inhibition suppresses KL tumor growth in mice." (PMID 34109280, 2021). "Investigating the molecular determinants governing the LKB1‐deficient cancer stemness is of particular importance for better understanding of KL tumor plasticity as well as providing novel therapeutic strategy." (PMID 33439550, 2021). "We found that phenformin treatment resulted in the decrease of ADC tumor numbers, blocked tumor cell proliferation, and induced cell apoptosis in KL ADC." (PMID 33439550, 2021). "Accumulating data indicate that klotho is a tumor suppressor in a wide array of malignancies, and designate the subdomain KL1 as the active region of the protein towards this activity." (PMID 34944918, 2021). "Histological analysis revealed that the tumor areas and sizes were significantly smaller in lungs of KrasLSL‐G12D/+Lkb1fl/flIl1f9−/− (KL9) mice than in the lungs of KL mice after tumor induction." (PMID 34369094, 2021). "Researches have shown that Klotho is not only an anti-aging gene but also a tumor suppressor gene that has the function of protecting kidney and inhibiting RCC." (PMID 35127476, 2021). "The promoter proximal region of the Klotho gene is reported to be hypermethylated in cancer, and transgenic overexpression or introduction of Klotho protein is observed to retard tumor growth in several animal models." (PMID 33553988, 2021). "According to another study, however, KL activates vascular endothelial growth factor receptor 2/p21-activated kinase 1, resulting in cell death resistance and favoring tumor migration and invasion." (PMID 33520985, 2020). "KL expression is negatively associated with TNM stage, tumor size, shorter overall and progression-free survival." (PMID 33520985, 2020). "Taken together, these results support the tumour suppressor function of Klotho and its modulation of IGF-1R signalling." (PMID 32585905, 2020). "Mice treated with soluble Klotho exhibited significantly reduced weight and volume of the orthotopic tumour." (PMID 32585905, 2020). "KL overexpression or treatment with recombinant KL or sKL decreases colony formation, cell proliferation, migration, and tumor invasion while inducing apoptosis and autophagy through inhibition of Wnt/β-catenin and IGF-1R/AKT/ERK signaling." (PMID 33520985, 2020). "Aberrant DNA methylation has been observed in numerous tumour types, neurodegenerative diseases, and genes related to ageing, including KLOTHO." (PMID 32585905, 2020). "KL seems to be an universal tumor suppressor in many different tumor entities owing to its inhibitory effect on pro-survival intracellular pathways including IGF-1R/PI3K/AKT or Wnt signaling." (PMID 33520985, 2020). "Overexpression of klotho inhibited cell proliferation in tumor tissues obtained from xenografts compared to control mice, as measured by immunohistochemistry (IHC)." (PMID 32614356, 2020). "Most studies indicate that KL functions as a tumor suppressor and modulates several signaling pathways such as insulin-like growth factor-1 (IGF-1), FGF, and Wnt/β-Catenin." (PMID 31681612, 2019). "Klotho, a widely recognized anti‐aging protein, was previously proposed to act as a tumor suppressor in CRC." (PMID 31545552, 2019). "From our analyses, it is interesting to see that the tumor suppressing effect of klotho also seems to be higher in males than in females." (PMID 30532070, 2019).
tumor (continued). "First, the result of RNA sequencing analysis showed the upregulation of Klotho mRNA in a tumor in a parotid gland compared to the adjacent normal tissue." (PMID 30627598, 2019). "Taken together, our present study uncovered a novel function of tumor suppressor, KL, in glycolysis regulation and provided the possible molecular mechanism." (PMID 29884183, 2018). "By inhibiting Insulin-Like Growth Factor-1-Receptor (IGF-1R) signaling, Klotho (KL) acts like an aging- and tumor-suppressor." (PMID 30441794, 2018). "If in the future the normal tissue of each patient were to be systematically sampled during tumor excision, it would be interesting to confirm these clinical results at the protein level by comparing KL abundance in DDLPS tumors with matched-adipose tissue." (PMID 30441794, 2018). "Analysis of tumor phenotypes indicated that Klotho reduces cell proliferation, clonogenicity, and has a major effect on drug sensitivity and Ca2+ homeostasis." (PMID 30441794, 2018). "Our previous study demonstrated that KL was a tumor suppressor in CRC and inhibited cell proliferation and metastasis, the malignancies of which were driven by and in part dependent on aerobic glycolysis." (PMID 29884183, 2018). "Taken together, our findings identified that Klotho performs as tumor suppressor and modulator of IGF-1R signaling in the DLBCL." (PMID 28153033, 2017). "Recently the Klotho protein has been proposed to be a tumor suppressor protein in many cancer types." (PMID 27999207, 2017). "Tumor suppressive activity of Klotho has been reported in several human solid malignancies, but never in hematological cancers." (PMID 28153033, 2017). "Our in vivo investigations demonstrated that upregulation of Klotho, either by LV-KL transfection or rhKL administration, congruously led to inhibitory effect in the tumor growth of xenograft model of DLBCL." (PMID 28153033, 2017). "In this study, our observations identified for the first time that Klotho, an anti-aging gene, as a potential tumor suppressor in DLBCL tumorigenesis." (PMID 28153033, 2017). "In an agreement with human SqCC, KL and xenograft SqCC tumours exhibit significantly increased AKT activity and downstream signalling directing the stabilization of HIF-1α and GLUT1 expression." (PMID 28548087, 2017). "Our findings establish that Klotho performs as a tumor suppressor and modulator of IGF-1R signaling in DLBCL." (PMID 28153033, 2017). "Consistent with the in vitro results, mice treated with Klotho overexpression cells revealed remarkable reduction in tumor volume compared to that transfected with empty vector." (PMID 28153033, 2017). "The expression of TNF-α and Hes1 (a downstream effector of Notch signaling) in tumor tissue was higher than both normal muscle and atrophic muscle, while the expression of Klotho [an anti-inflammatory factor] was lower." (PMID 27378829, 2016). "Klotho is an established tumor suppressor, epigenetically silenced in breast and other cancers since it inhibits signaling pathways, such as IGF-1, PI3K, WNT, and TGFβ." (PMID 26556877, 2016). "Promoter hypermethylation in KLOTHO gene was detected in 86% (43/50) of tumor tissues and 14% (7/50) of adjacent normal tissues." (PMID 27844013, 2015). "Further, there was also a decrease in bone morphogenetic protein 2 (BMP2), cMyc, and ALDH levels while Klotho, a tumor suppressor, was up-egulated with retinal treatment." (PMID 26819566, 2015). "Recently, KLOTHO was identified as a potential tumor suppressor and a candidate target for epigenetic silencing in various cancers." (PMID 27844013, 2015). "For example, klotho is observed to induce cell apoptosis and inhibit tumor growth through inhibiting insulin/ insulin-like growth factor-1 (IGF-1) signaling." (PMID 23432957, 2013). "In this study, klotho was identified a tumor suppressor, which inhibited tumor cell proliferation, induced cell apoptosis and autophagy in GC." (PMID 23432957, 2013).
tumor (continued). "Although Klotho has been characterized as a potential tumor suppressor in tumorigenesis of various human cancers, the functional role and molecular mechanism of Klotho in hepatocarcinogenesis remains poorly understood." (PMID 23516476, 2013). "Although Klotho was recently reported to exhibit tumor suppressive properties during various malignant transformations, the functional role and molecular mechanism of Klotho in hepatocarcinogenesis remains poorly understood." (PMID 23516476, 2013). "Klotho is observed in several tumors to induce cell apoptosis and inhibit tumor growth through inhibiting insulin/IGF-1 signaling by inhibiting the tyrosine phosphorylation of IGF-1 receptor." (PMID 23432957, 2013). "KL has been found to function as tumor suppressor in various cancers like breast, pancreas, lung, and cervix." (PMID 23533570, 2013). "Recently, KLOTHO was identified as a potential tumor suppressor that inhibits the IGF-1 pathway and activates the FGF pathway in human breast cancer." (PMID 20482749, 2010). "Hnf4a and Elovl7 showed higher expression level in the tumor bearing mice, compared to control, suggesting that tumor growth in the lung increased the level of genes involved in lipid metabolism in distal hepatocyte tissues in the KL mouse model." (PMID 40236168, 2025). "Additionally, Klotho overexpression has been observed to hinder cell proliferation and promote apoptosis in A549 cells, suggesting its potential as a tumor suppressor." (PMID 40134808, 2025). "In human colorectal adenocarcinoma cells (HT-29), exogenous Klotho may be a helpful therapy due to the elimination of apoptosis resistance and lower tumour activity." (PMID 40119098, 2025). "The data confirming tumor regression in several “in vivo” models that are not Klotho-deficient support further evaluation of Klotho as a candidate therapeutic target." (PMID 39796185, 2025). "Suppressing the UPR partially diminished the function of Klotho as a tumor suppressor." (PMID 40004457, 2025). "Klotho is described as a tumor suppressor in several solid tumors and hematological malignancies." (PMID 40004457, 2025). "The tumor suppressive sequence within the KL1 domain of the hormone Klotho was determined." (PMID 39796185, 2025). "The study concluded that Klotho could act as a tumor suppressor in HCC, with hypermethylation and acetylation contributing to its loss of expression." (PMID 40004457, 2025). "In summary, the data indicate that we are just beginning to find out whether circulating Klotho could serve as a serum marker for the early diagnosis of various tumor types." (PMID 39796185, 2025). "Hence, Klotho functions as a tumor suppressor, with its expression being intricately connected to both the progression and prognosis of PDAC." (PMID 40004457, 2025). "Thus, the literature considers KLOTHO as a critical tumor suppressor, influencing in cell proliferation, survival, autophagy, and resistance to anti-cancer therapies." (PMID 39199335, 2024). "Klotho plays a key role in tumor genesis, its progression, and its prognosis." (PMID 37425590, 2023). "Moreover, in a xenograft model treated with either Klotho overexpression vector or recombinant human Klotho administration presented restrained tumor growth and lower Ki67 staining." (PMID 37047075, 2023). "As a valuable tumor suppressor gene, Klotho protein expression is found to be low in various cancerous tissues, including kidney, breast, liver, lung, pancreatic, and others, indicating its ability to inhibit tumor cell growth." (PMID 37726833, 2023). "Although combination therapy induces ferroptosis, other mechanisms might be involved in the reduction of KL tumor growth, which requires further investigation." (PMID 36702816, 2023). "KL mice were randomized, and initial tumor volumes were measured by MRI." (PMID 37035141, 2023).
tumor (continued). "The present review analyzed research articles published between 2012 and 2022 in the Cochrane and Scopus scientific databases to study the role of Klotho in cancer and their potential as tools for diagnosing specific cancer types, predicting tumor aggressiveness and prognosis." (PMID 37958253, 2023). "In addition, KLOTHO, or its protein product αKlotho, has been shown to exert a tumor suppressor effect in BC and OC, among other tumors." (PMID 37109525, 2023). "Enforced expression of Klotho could significantly induce cell apoptosis and inhibited tumor growth in DLBCL." (PMID 37047075, 2023). "Another important aspect is the role of Klotho as a tumor suppressor molecule." (PMID 35903083, 2022). "The membrane-bound and soluble forms of Klotho both have tumor suppressor effects." (PMID 35903083, 2022). "There is considerable evidence that Klotho is a tumor suppressor molecule, as reviewed elsewhere." (PMID 35903083, 2022). "Klotho is a tumor suppressor that has previously been shown to interact with the mTOR pathway." (PMID 36220392, 2022). "Furthermore, we found that SHANK1 increases the protein degradation of Klotho (KL), an important tumor suppressor, through ubiquitination-dependent pathway." (PMID 35468874, 2022). "In experimental tumor models, Klotho has anti-tumor effects in vivo and/or in vitro." (PMID 35903083, 2022). "The absence of klotho expression was significantly associated with tumor grade, Ki-67 expression, and metastasis." (PMID 35666743, 2022). "Similarly, in vivo, forced tumor overexpression of Klotho, or systemic administration of s-Klotho, inhibited the growth of several types of tumors." (PMID 35903083, 2022). "In addition, klotho has been found to inhibit tumor growth by acting on the FGF, phosphatidylinositol 3-kinase/Akt, WNT, transforming growth factor β, and unfolded protein response pathways." (PMID 35666743, 2022). "The percentage of high klotho expression was significantly lower as the tumor malignancy increased." (PMID 35666743, 2022). "To investigate the histopathology-selective phenotypes of NSCLC cancer, including potential differences in their transplantation capacity in vivo, we first assessed the tumor-forming capacity of bulk cell populations isolated from GEMM-derived KL;ASC and KL;AC cells outside of the lung." (PMID 36355420, 2022). "Importantly, tumor weights negatively correlated with human klotho blood levels in mice (|r| > 0.729)." (PMID 34944918, 2021). "On the other hand, the ability of Klotho to restore drug sensitivity appears to involve downregulation of autophagy activity in some cases, highlighting the dual role of Klotho in regulating autophagy in tumor cells." (PMID 34737707, 2021). "In conclusion, this study provides evidence that klotho is a tumor suppressor in PDAC." (PMID 34944918, 2021). "The present study establishes the role of klotho as a tumor suppressor in PDAC." (PMID 34944918, 2021). "Studies in various types of cancer suggest that Klotho acts as a tumor suppressor." (PMID 34737707, 2021). "In conclusion, this study identified klotho as a potent tumor suppressor in PDAC." (PMID 34944918, 2021). "Klotho is a potent tumor suppressor in numerous malignancies, including gastrointestinal cancers." (PMID 34944918, 2021). "IHC staining showed that only ALKBH5 expression was higher in KL than that of in K tumor tissues." (PMID 34016959, 2021). "Evidence also shows that the anti-tumor effects of klotho are involved in induction of apoptosis." (PMID 32614356, 2020). "It is suggested that maintaining normal cell cycle and division might be an important tumor suppression mechanism of Klotho." (PMID 32899868, 2020). "In mice, KL-expressing A2780 tumor cells grow more slowly than KL-negative tumor cells." (PMID 33520985, 2020).